FH (fumarate hydratase)
Diseases named in the same sentence as FH in open-access papers (continued):
Sharing a sentence is not in itself a finding about the gene and the disease.
leiomyoma (continued). "In summary, this case contributes to the limited literature by describing a rare presentation of FH-deficient leiomyoma associated with pelvic congestion syndrome, highlighting the importance of considering vascular complications in the clinical spectrum of this entity." (PMID 41438660, 2026). "Management of FH-deficient leiomyomas may involve conventional treatments like surgery and hormonal therapy but also requires careful monitoring and genetic counseling for associated malignancies." (PMID 40002168, 2025). "Indeed, considering the peculiar biological behavior of FH-deficient leiomyomas, surgery remains the recommended treatment for these patients." (PMID 40002168, 2025). "One of these FH variants, c.1301G>A (p.Cys434Tyr),had been previously identified in a proband with multiple cutaneous and uterineleiomyomas and a history of a first-degree relative who had undergone myomectomy foruterine fibroids." (PMID 39705504, 2024). "Herein, we report a case of fumarate hydratase deficient leiomyoma." (PMID 38784227, 2024). "Background and Objectives: Mutations in succinate dehydrogenase (SDH) and fumarate hydratase (FH) give rise to various familial cancer syndromes, with these alterations being characteristic of certain types of histomorphologically specific leiomyomas that hold significant predictive value." (PMID 38793008, 2024). "FH alterations are mostly restricted to FH-deficient leiomyoma and leiomyoma with bizarre nuclei." (PMID 37466765, 2024). "Indeed, we recently analyzed publicly available leiomyoma data and reclassified two leiomyomas as FH-deficient partly based on the expression of AKR1B10." (PMID 36068196, 2022). "Affected females may present with early-onset multiple uterine leiomyomas (fibroids) and FH mutations are a rare cause of inherited phaeochromocytoma/paraganglioma." (PMID 29680948, 2018). "Furthermore, FH-deficient tumors have been shown to display distinct molecular signatures and immunohistochemical profiles, which help to differentiate them from other leiomyomas." (PMID 40002168, 2025). "FH deficiency can sporadically occur in some leiomyosarcomas and is rare in conventional leiomyomas, emphasizing the need for careful distinction between leiomyoma with bizarre nuclei, leiomyosarcoma, and smooth muscle neoplasms of uncertain malignant potential (STUMP)." (PMID 38793008, 2024). "In addition to nuclear features, specific histological features have been described for these leiomyomas, including dilated staghorn vessels, perinuclear halos, and eosinophilic cytoplasmic inclusions, which are quite specific to leiomyoma with FH deficiency, similar to that observed in our cases." (PMID 38793008, 2024). "The study concluded that while FH-deficient leiomyomas are a hallmark of HLRCC, they also occur in a small percentage of unselected leiomyomas due to somatic mutations." (PMID 40002168, 2025). "Leiomyoma-associated driver alterations in MED12, HMGA2, and FH have been reported in up to one-third of uterine leiomyosarcomas." (PMID 41162745, 2025). "Immunohistochemistry can now detect FH protein deficiency in leiomyoma tissue, which represents either a germline mutation associated with HLRCC or a somatic mutation within the leiomyoma." (PMID 41000563, 2025). "Three well-established driver alterations in leiomyomas are MED12 mutations, chromosomal rearrangements leading to HMGA2 overexpression, and biallelic mutations resulting in FH-deficiency, which together account for 80–90% of the tumors." (PMID 41162745, 2025). "Reported FH-d LMS showed global FH loss, with one case displaying small subclonal LMS within a background leiomyoma, both were FH-d." (PMID 38642139, 2024). "Biallelic inactivation of the fumarate hydratase gene is characteristic mainly of a rare type of leiomyoma with bizarre nuclei." (PMID 37987267, 2023).
leiomyoma (continued). "Fibroids are frequently associated with genetic alterations affecting mediator complex subunit 12 (MED12), fumarate hydratase (FH), high mobility group AT-hook 2 (HMGA2) and collagen, type IV alpha 5 and alpha 6 (COL4A5-COL4A6)." (PMID 37113812, 2023). "The driver mutations critical to leiomyoma development and progression include MED12 (mediator complex subunit 12), HMGA2 (high mobility group AT-hook 2), FH (fumarate hydratase), and COL4A5/6 (collagen type IV, alpha 5, and alpha 6)." (PMID 35641855, 2022). "We and others have previously shown that MED12, HMGA2, and FH aberrations result in distinct global gene expression patterns, suggesting that leiomyomas can be classified by gene expression profiling." (PMID 33352722, 2020). "All leiomyomas showed dysregulation of 70 metabolites, and distinct metabolomics profiles were seen for different genetic subtypes of leiomyomas (i.e.; FH, MED12, HMGA2)." (PMID 33371433, 2020). "Again, the samples clustered clearly into four similar groups, and the two HMGA1 overexpressing leiomyomas displayed clear expression patterns of leiomyomas of the FH subtype." (PMID 33352722, 2020). "Principal component analysis using the 3′RNA sequencing data revealed that the 49 (44 leiomyomas + 5 myometrium) samples and 11 technical replicates grouped according to the predetermined mutation status of MED12, HMGA2, and FH." (PMID 33352722, 2020). "We screened the full coding sequence and splice junctions of FH in all of the leiomyomas and leiomyosarcomas." (PMID 12177782, 2002). "Leiomyosarcomas, by contrast, show significant cytologic atypia, high mitotic activity, and areas of coagulative necrosis, features not present in FH-deficient leiomyomas." (PMID 41438660, 2026). "Leiomyoma with bizarre nuclei and fumarate hydratase-deficient leiomyoma are excluded due to the absence of atypical/bizarre tumour cells." (PMID 41227011, 2025). "Germline mutation carriers often undergo regular surveillance and may consider expanded FH screening (for example, young ladies with fibroids) in order to provide an early curative intervention and detection of RCC." (PMID 40002168, 2025). "Fibroid tumors stratify into four main subtypes that are dependent on the mutational status of mediator of transcription subunit 12 (MED12), fumarate hydratase (FH), high mobility group AT-hook 2 (HMGA2) translocations, and collagen (COL4A5-COL4A6) gene deletions." (PMID 32094355, 2020). "Unlike conventional leiomyomas, the histopathological UL variants (8.5%, 8/94) displayed 2SC positivity as a sign of FH deficiency." (PMID 28592321, 2017). "Only 5% (seven out of 129) of the leiomyomas showed allele imbalance at 1q42-q43 and no somatic mutations in fumarate hydratase were observed." (PMID 12177782, 2002). "Due to the known link between FH mutations and fibroids associated with HLRCC, women seeking reproductive assistance undergoing comprehensive reproductive counselling and treatment including genetic carrier screening should be screened for FH mutations and counselled accordingly." (PMID 37663422, 2023). "In addition, we identified AKR1B10 expression in nine leiomyomas with no indication of FH-deficiency or alterations affecting MED12 or HMGA2." (PMID 36068196, 2022). "In the remaining patient, sequencing of the FH exon regions (using RNA extracted from a leiomyoma) did not reveal any genetic variants; however, this does not exclude gross deletions or the presence of a pathogenic variant in the promotor region or in the intron regions." (PMID 33461594, 2021). "The absence of FH immunohistochemical staining in uterine leiomyoma cells suggests FH mutation." (PMID 34889279, 2021). "(B) All cartilage tumours on TMA lacked detection of succinated protein using 2-SC staining, indicating absence of FH mutations, inset shows positive staining for 2-SC in a leiomyoma derived from a patient with a germline FH mutation as positive control (Scores were rounded to zero decimal places)." (PMID 28484589, 2017).
leiomyoma (continued). "Notably, FH was underexpressed in both HLRCC fibroids and nonsyndromic fibroids, suggesting that FH downregulation may also occur in non-syndromic fibroids, warranting further investigation into metabolic alterations and adaptations of fibroids, even in the absence of FH mutations." (PMID 41300720, 2025). "The samples were analyzed together with a previously published dataset of 44 leiomyomas with a driver alteration in MED12, HMGA2, or FH as well as five myometrium samples." (PMID 35822448, 2023). "Indeed, 80–90% of leiomyomas harbor one of three genetic changes: a hotspot mutation in mediator complex subunit 12 (MED12), a chromosomal aberration resulting in upregulation of high mobility group AT-hook 2 (HMGA2), or biallelic loss of fumarate hydratase (FH)." (PMID 36068196, 2022). "Indeed, 80−90% of leiomyomas harbor one of three genetic changes: a hotspot mutation in mediator complex subunit 12 (MED12), a chromosomal aberration resulting in significant overexpression of high mobility group AT-hook 2 (HMGA2), or biallelic loss of fumarate hydratase (FH)." (PMID 33352722, 2020). "Recently, it has been suggested that leiomyomas with bizarre nuclei can be divided into two subtypes based primarily on nuclear features; some tumors show significantly higher rates of HMGA2 immunoreactivity and frequent MED12 mutations and the others may occasionally be related to FH mutations." (PMID 28592321, 2017). "Leiomyosarcomas did not cluster together based on the presence of the established leiomyoma-associated driver mutations, unlike leiomyomas, which clustered according to the underlying MED12, HMGA2, or FH alteration." (PMID 41162745, 2025). "A 30-year-old Chinese female presented with multiple myomas treated by myomectomy, and the final pathologic reports proved the lesions to be leiomyomas with bizarre nuclei with FH status unclear (did not obtain testing in the local hospital)." (PMID 36981015, 2023). "Here, we performed 3′RNA‐sequencing with 111 leiomyomas that had been previously classified as negative for a MED12 mutation, HMGA2 overexpression, and FH‐deficiency by Sanger sequencing or immunohistochemistry." (PMID 35822448, 2023). "This motivated us to explore the expression pattern of HMGA1 in our FFPE dataset, revealing significant upregulation of HMGA1 in leiomyomas of the FH subtype, but not in leiomyomas of the MED12 and HMGA2 subtypes." (PMID 33352722, 2020). "None of the tumors displayed simultaneously more than one leiomyoma driver alteration, indicating that MED12 mutations, HMGA2 overexpression, and biallelic FH inactivation are mutually exclusive." (PMID 28592321, 2017). "Conversely, no FH positivity was observed in the leiomyoma cells." (PMID 38793008, 2024). "In addition, although the great majority of leiomyomas can be explained by defects in MED12, HMGA2, or FH, there is a small subset of leiomyomas where the driver alteration is unknown." (PMID 33352722, 2020). "Aberrations in MED12, HMGA2, FH, and SRCAP complex genes account for most leiomyomas, but ~10% of leiomyomas do not harbor defects in any of these genes." (PMID 35822448, 2023). "As expected, we detected significant upregulation of PLAG1 in leiomyomas of the HMGA2 and FH subtypes, but not in leiomyomas of the MED12 subtype." (PMID 33352722, 2020).
kidney cancer (47 papers, 2011 to 2026). Primary or metastatic malignant neoplasm involving the kidney. "HLRCC is a rare autosomal dominant syndrome characterized by a predisposition to smooth muscle tumors and aggressive kidney cancer, driven by germline mutations in the FH gene, consisting of heterozygous germline FH mutations at chromosome 1q42.3-q43." (PMID 41585615, 2026). "FH deficiency is associated with the development of certain types of kidney cancer, with mutations in the FH gene resulting in a highly invasive and metastatic phenotype with poor prognosis." (PMID 40461489, 2025). "Nucleotide salvage should be further investigated as a targetable node, as has been explored in kidney cancers with FH mutation and subsequent reliance on purine salvage." (PMID 40324880, 2025). "Fumarate hydratase (FH) mutated papillary renal cell carcinoma is an aggressive variant of kidney cancer that poorly responds to conventional targeted therapies and immunotherapy." (PMID 39496729, 2024). "Most cancers show evidence of aerobic glycolysis, and in several kidney cancers, a deficiency in aerobic respiration appears to be selected for by genetic mutation (e.g. FH mutations in FH-RCC or Complex I mutations in renal oncocytoma)." (PMID 39149323, 2024). "For likely pathogenic mutations, FANCM and FH ranked top for kidney cancer, RAD51C ranked top for bladder cancer, and ATM and PMS2 ranked top for prostate cancer." (PMID 36451132, 2022). "Fumarate, as an oncometabolite, was discovered in kidney cancer and is associated with inactivating mutations in fumarate hydratase (i.e., fumarase)." (PMID 33806675, 2021). "HLRCC syndrome, characterized by the loss-of-function mutation in the FH gene, is associated with aggressive kidney cancers, prone to metastasize early." (PMID 31963199, 2020). "FH mutation in kidney cancer has been shown to induce an increase in glucose uptake, glycolytic rate, and contribution of glucose to the pentose phosphate pathway." (PMID 31817761, 2019). "In this study, we uncovered a metabolic effect of proteasome inhibitors in FH-deficient kidney cancer cells in vitro and in vivo." (PMID 31804603, 2019). "So far, there have been several case reports regarding HLRCC-associated kidney cancer, however, most of those were reporting the mutation analysis of FH, pathological features, and clinical course." (PMID 26983443, 2016). "On the other hand, it was also proven that LDHA inhibition results in increasing apoptosis of the tumor cells in FH-deficient kidney cancer and is considered in therapeutic strategy for patients with kidney cancer." (PMID 24885701, 2014). "It has been demonstrated that the glucose-mediated generation of cellular reactive oxygen species in an FH-deficient kidney cancer cell line results in the stabilization of hypoxia-inducible factor (HiF) 1-α." (PMID 24348776, 2014). "Fumarate hydratase (FH)-deficient kidney cancer undergoes metabolic remodeling, with changes in mitochondrial respiration, glucose, and glutamine metabolism." (PMID 23967283, 2013). "In this report, we demonstrate for the first time reduced FH expression at the mRNA and protein levels in clear cell renal carcinoma, the most common histological variant that accounts for the majority of kidney cancers." (PMID 21695080, 2011). "Here we report that FH mRNA and protein expression are reduced in clear cell renal cancer, the most common histologic variant of kidney cancer." (PMID 21695080, 2011). "However, certain variants in one copy of the FH gene predispose to a form of kidney cancer that is often aggressive and tends to be diagnosed at a late stage." (PMID 37339848, 2024). "For instance, mutations in SDH in hereditary paragangliomas and fumarate hydratase (FH) in leiomyomatosis and kidney cancers lead to the accumulation of succinate and fumarate, thus reducing the degradation of HIF and promoting the expression of multiple glycolytic enzyme genes." (PMID 37108242, 2023).
kidney cancer (continued). "HLRCC‐associated kidney cancers were initially recognized by their unique histologic features; however, a spectrum of growth patterns has been demonstrated and recent classifications have recognized FH deficiency as a distinct entity." (PMID 32463173, 2020). "Indeed, some cancers, like fumarate hydratase (FH)-deficient kidney cancer, are explicitly caused by loss-of-function mutations in enzymes involved in important metabolic pathways, and these tumors adjust their metabolism accordingly." (PMID 30180879, 2018). "It has been established that in Fumarate Hydratase (FH)-deficient kidney cancer, there is impaired oxidative phosphorylation with metabolic shift to aerobic glycolysis to generate ATP required for the increased energy demand of the rapidly proliferating tumor cells." (PMID 24885701, 2014). "In kidney cancer, mutations in the enzymes of the TCA cycle such as succinate dehydrogenase (SDH) and fumarate hydratase (FH) lead to impairment of oxidative metabolism." (PMID 34822425, 2021). "The increased levels of succinate and fumarate have been asso-ciated in other cancer types (e.g., paraganglioma, pheochromocytoma or kidney cancers) with mutation in the enzymes succinate dehydrogenase (SDH) and fumarate hydratase (FH), respectively." (PMID 33808897, 2021). "There are many reports on genes associated with kidney cancer pathogenesis, including VHL, FH, MET, FLCN, etc.." (PMID 32850947, 2020). "Kidney cancer is associated with several gene mutations including Von-Hippel-Lindau (VHL), fumarate hydratase (FH) and succinate dehydrogenase (SDH) and accounts for 3% of all cancers with 2% of the total cancer deaths in the U.S." (PMID 22804960, 2012). "The findings suggest that genes associated with kidney cancer, including VHL, MET, FH, FLCN, TSC1, TSC2, and SDH, are involved in metabolic pathways linked to oxygen and iron or nutrient sensing, thus characterizing kidney cancer as a cellular metabolic disease." (PMID 35873461, 2022). "Multiple genes linked with kidney cancer, including the VHL, MET, FLCN, fumarate hydratase, succinate dehydrogenase, TSC1, TSC2, and TFE3, were identified by genomic studies and have significantly altered the ways in which patients with kidney cancer are managed." (PMID 29254180, 2017). "FH mutation plays a role in tumorigenic feature, a metabolic shift to aerobic glycolysis, and increased an anti-oxidant response phenotype in HLRCC-associated kidney cancer." (PMID 26983443, 2016). "However, the FH variant found in this man is both off-target (it does not explain his muscle weakness) and uncertain (its link to kidney cancer is theoretical, not established)." (PMID 37339848, 2024). "Finally, the observation that, unlike normal kidney epithelial cells, FH-deficient kidney cancer cells are auxotrophic for arginine provides potential new therapeutic interventions for these cancers." (PMID 24280230, 2013). "Recently, several characteristic kidney cancer-related genes, including VHL, MET, FLCN, TSC1, TSC2, FH, and SDH, have been reported to affect the metabolic stress response." (PMID 33686951, 2021). "Several known genes related kidney cancer, such as von Hippel-Lindau (VHL), fumarate hydratase (FH) and succinate dehydrogenase (SDH) are involved in pathways that respond to metabolic stress." (PMID 24636201, 2014). "Previous studies have shown that seven known kidney cancer genes, VHL, MET, FLCN, TSC1, TSC2, FH, and SDH, are involved in pathways that respond to metabolic stress or nutrient stimulation, suggesting that kidney cancer is a disease of dysregulated cellular metabolism." (PMID 31649873, 2019).